PRC1 (protein regulator of cytokinesis 1)
Diseases named in the same sentence as PRC1 in open-access papers (continued):
Sharing a sentence is not in itself a finding about the gene and the disease.
liver cancer (4 papers, 2019 to 2024). An epithelial or non-epithelial malignant neoplasm that arises from the liver. "In liver cancer, PRC1 has been found to be abnormally associated with chemotherapy resistance." (PMID 35387129, 2022). "The top modular genes, TOP2A, CDC20, PRC1, CCNB2, and NUSAP1, were highly associated with HCC onset and development; high expression of TOP2A, CDC20, or CCNB2 was correlated with poor survival time in TCGA liver cancer patients, implying their potential as biopsy-based prognostic markers." (PMID 31001331, 2019). "Altogether, PRC1 and RACGAP1 are identified both as prognosis markers for early HCC detection and therapeutic targets for liver cancer and liver CSCs, adding additional layers for the early prognosis and therapy of HCC." (PMID 35445033, 2022). "Therefore, PRC1 and RACGAP1 are identified as prognosis markers for early HCC and therapeutic targets for liver cancer and liver CSCs." (PMID 35445033, 2022).
melanoma (4 papers, 2016 to 2022). A malignant, usually aggressive tumor composed of atypical, neoplastic melanocytes. "Subsequently, we examined the regulatory effect of Prc1 and Nuf2 in human melanoma A375 cells, respectively." (PMID 35393397, 2022). "In melanoma cells, PRC1 and PRC2 negatively regulate oncogene-induced senescence (OIS)." (PMID 34638331, 2021). "MIR31HG and ANRIL are two lncRNAs that regulate this genomic locus through interactions with PRC1 and PRC2 in melanoma." (PMID 34638331, 2021). "We believe that PRC1 and NUF2 can be used as targets for the treatment of melanoma." (PMID 35393397, 2022).
nasopharyngeal carcinoma (4 papers, 2021 to 2023). A carcinoma arising from the nasopharyngeal epithelium. "Functional experiments suggest PTPRG-AS1 acts as a miRNA “sponge” to regulated protein regulator of cytokinesis 1 (PRC1) in nasopharyngeal carcinoma." (PMID 34876904, 2021). "Besides, in nasopharyngeal cancer, lncRNA PTPRG-AS1 enhanced radioresistance via miR-194-3p/PRC1." (PMID 35600868, 2022).
non-small cell lung carcinoma (4 papers, 2009 to 2025). A group of at least three distinct histological types of lung cancer, including non-small cell squamous cell carcinoma, adenocarcinoma, and large cell carcinoma. "This study aims to examine the function of PRC1 in non-small cell lung cancer (NSCLC) cells and investigates its regulatory mechanisms." (PMID 40665337, 2025). "The clonal cell lines in which PRC1, ANLN and YB1 are tagged originate from the same parental cell (H1299 non small cell lung cancer cell line)." (PMID 19381343, 2009). "Importantly, the tumor area in mice infected with the lentivirus expressing the PRC1-specific shRNA was significantly smaller compared to mice infected with the virus expressing the control shRNA, indicating a requirement for PRC1 in K-RAS-driven non-small cell lung cancer in vivo." (PMID 29435157, 2018).
diabetes (3 papers, 2018 to 2025). "Although ZFAND6 and PRC1 were identified as diabetes related loci in western populations, only recently the role of ZFAND6 and PRC1 loci have been described in insulin secretion and beta cell function through animal models." (PMID 37738238, 2023).
Infertility (3 papers, 2020 to 2023). "Thus, deficiencies in PRC1 function may underlie specific instances of premature ovarian failure and infertility in human females." (PMID 35948547, 2022). "We found that human oocytes, even those of young women with no history of infertility, carry Prc1-less kinetochores, although our data do not exclude the possibility that an undetectable pool of Prc1 at kinetochores contributes to spindle bipolarization." (PMID 32461611, 2020). "Importantly, kinetochore Prc1 was consistently undetectable in oocytes of young women (<30 years old) with no history of infertility." (PMID 32461611, 2020). "Although we did not observe complete infertility using Amh-Cre (presumably due to the repopulation of Sertoli cells that escaped Cre-mediated recombination), smaller testis size and abnormal tubule organization of cKO testes suggest that PRC1 is critical for physiological functions of Sertoli cells." (PMID 37542070, 2023).
liposarcoma (3 papers, 2017 to 2025). A usually painless malignant tumor that arises from adipose tissue. "Considering the known tumour-promoting roles of TOP2A, PRC1, and PLK1, inhibiting these proteins by miR-143, therefore, helps inhibit liposarcoma progression." (PMID 39736850, 2025). "MiR-143 inhibits proliferation, induces apoptosis and cytokinesis of dedifferentiated liposarcoma cells by lowering BCL2, TOP2A, PRC1 and PLK1 expression." (PMID 28036291, 2017). "Functional assay revealed that miR-143 could repress the expressions of topoisomerase 2-alpha (TOP2A), protein regulator of cytokinesis 1 (PRC1), and polo-like kinase 1 (PLK1) to inhibit liposarcoma cell growth and trigger apoptosis." (PMID 39736850, 2025).
medulloblastoma (3 papers, 2013 to 2023). A malignant, invasive embryonal neoplasm arising from the cerebellum. "Multiple other genes belonging to PRC1 and PRC2 complexes, including BMI1, EED and SUZ12 have been found upregulated either in specific medulloblastoma subgroups or across medulloblastoma generally." (PMID 29759978, 2018). "Our finding that Eed deletion did not affect levels of H2AK119 monoubiquitylation suggests that PRC1 activity was not altered in EedcKO CGNPs or medulloblastomas." (PMID 36635771, 2023).
meningioma (3 papers, 2013 to 2019). A generally slow growing tumor attached to the dura mater. "In accordance with our findings, the remaining four top genes were previously found to be either upregulated (UBE2C and PRC1) or downregulated (LEPR and MN1) in WHO grade II and III meningiomas." (PMID 26894859, 2016). "In malignant meningiomas, the HOXA gene locus “poised” by PRC1 and PRC2 targeting was likely to undergo epigenetic switching, gaining DNA methylation for permanent gene silencing." (PMID 23349797, 2013). "The positive correlation of PRKACA with NF2 gene expression, which is downregulated in meningioma, may support this view, as well as the negative correlation of PRKACA expression with the four upregulated genes typically found in recurrent meningiomas (CDC2, MLF1IP, CKS2, and PRC1)." (PMID 31671850, 2019).
myeloma (3 papers, 2018 to 2024). "In support of this notion, the combination of EZH2 and BMI-1 (PRC1) inhibitors have synergistic anti-myeloma activity using HMCLs and CD138+ myeloma cells isolated from newly diagnosed or relapsed MM patients." (PMID 30761216, 2018).
type 2 diabetes (3 papers, 2011 to 2025). "PRC1, crucial for cytokinesis, has been identified as a susceptibility gene for type 2 diabetes." (PMID 40399988, 2025). "We confirm the role of ZFAND6, PRC1 and TMEM154 in the pathophysiology of type 2 diabetes among Indians." (PMID 37738238, 2023).
atherosclerosis (2 papers, 2022 to 2023). A disease characterized by the build-up of fatty material and calcium deposition in the arterial wall resulting in partial or complete occlusion of the arterial lumen. "Further studies are necessary to validate the roles of PRC1 in the development of atherosclerosis." (PMID 36894991, 2023).
autism (2 papers, 2022 to 2025). Persistent deficits in social interaction and communication and interaction as well as a markedly restricted repertoire of activity and interest as well as repetitive patterns of behavior. "Auts2 encodes a PRC1-associated transcriptional activator essential for normal neuronal gene expression, and haploinsufficiency of Auts2 is associated with ID and autism." (PMID 35731217, 2022).
B cell lymphoma (2 papers, 2025). "In B-cell lymphoma, PRC1 upregulation silences H2K119Ub, inhibiting tsMHC-II upregulation and contributing to immunotherapy resistance." (PMID 40495188, 2025). "In our current studies, we demonstrated that inhibition of PRC1 activity by its specific small molecule inhibitor RB-3 could at least partially rescue the transcriptional defect induced by BAP1 depletion in B cell lymphoma cells." (PMID 39817454, 2025). "Additionally, we demonstrated that pharmacological inhibition of polycomb repressive complex 1 (PRC1) — which deposits histone H2K119Ub and opposes BAP1 activity — can restore MHC-II gene expression in BAP1-deficient B cell lymphoma cells." (PMID 39817454, 2025). "In our current studies, we demonstrated that PRC1 is responsible for the transcriptional repression of MHC-II genes upon BAP1 depletion, as inhibition of PRC1 could largely rescue the gene-expression defect in BAP1-depleted B cell lymphoma cells." (PMID 39817454, 2025). "Finally, to determine a potential combination effect of both PRC1 and PRC2 inhibitors on reactivation of MHC-II gene expression in BAP1-deficient B cell lymphoma cells, we treated BAP1-KO A20 cells with RB-3 or/and GSK126 for 6 days, followed by Western blot and FACS analysis." (PMID 39817454, 2025). "In summary, our studies have uncovered a potential role of histone H2AK119 deubiquitinase BAP1 and the epigenetic balance between PRC1 and BAP1 in regulating MHC-II gene expression and TME in B cell lymphoma cells." (PMID 39817454, 2025). "Therefore, we endeavored to further investigate the impact of the PRC1 inhibitor on H3K27me3 levels and MHC-II gene expression in B cell lymphoma cells." (PMID 39817454, 2025).
chronic myelomonocytic leukemia (2 papers, 2021 to 2023). A myelodysplastic/myeloproliferative neoplasm which is characterized by persistent monocytosis, absence of a Philadelphia chromosome and BCR/ABL fusion gene, fewer than 20 percent blasts in the bone marrow and blood, myelodysplasia, and absence of PDGFRA or PDGFRB rearrangement. "BCOR and BCORL1 proteins function as components of PRC1.1, a noncanonical PRC1, and are frequent targets of somatic mutations in AML, sAML, MDS, and chronic myelomonocytic leukemia (CMML)." (PMID 33799787, 2021).
Kabuki syndrome (2 papers, 2020 to 2025). Kabuki syndrome (KS) is a multiple congenital anomaly syndrome characterized by typical facial features, skeletal anomalies, mild to moderate intellectual disability and postnatal growth deficiency. "In Kabuki syndrome, mutations in histone lysine methyltransferase MLL4 and demethylase UTX reduce their ability to form phase-separated condensates, impairing recruitment of MED1/BRD4 and exclusion of PRC1/2." (PMID 40507965, 2025).
liver fibrosis (2 papers, 2019 to 2021). "We aim to investigate effect and mechanism of PRC1 on liver fibrosis." (PMID 31867100, 2019). "The “protein regulator of cytokinesis 1” (PRC1), which regulates the Wnt/β-catenin signaling pathway, may induce Gli1-dependent osteopontin expression to contribute to liver fibrosis." (PMID 34805276, 2021).
Luo-Schoch-Yamamoto syndrome (2 papers, 2025). "De novo dominant missense variants in RNF2, the principal E3 ligase of PRC1, are the genetic basis of Luo-Schoch-Yamamoto syndrome." (PMID 40831499, 2025).
lymphoma (2 papers, 2018 to 2025). A malignant (clonal) proliferation of B- lymphocytes or T- lymphocytes which involves the lymph nodes, bone marrow and/or extranodal sites. "Similarly, PRC1 and CDC25C mRNA levels in various AML cell lines were significantly higher compared to lymphoma cell lines." (PMID 40034437, 2025).
myeloid malignancies (2 papers, 2021 to 2022). "It has also been shown that mutant ASXL1 disrupts the function of PRC1 and causes derepression of expression in target genes, which possibly leads to the development of myeloid malignancies, including MDS." (PMID 35821550, 2022). "Overexpression of BMI1, encoding for another subunit of the PRC1 complex that stimulates the ubiquitinase activity of PRC1 toward H2AK119 and promotes DSB repair, has been observed in myeloid malignancies." (PMID 34885058, 2021).
oral cancer (2 papers, 2018 to 2025). "Based on these, we have forecasted that protein regulator of cytokinesis 1 (PRC1) is one of the potential targets for the treatment of oral cancer." (PMID 29752448, 2018).
osteosarcoma (2 papers, 2020 to 2025). A usually aggressive malignant bone-forming mesenchymal neoplasm, predominantly affecting adolescents and young adults. "Similarly, the B-cell-specific Moloney murine leukemia virus integration site 1 (BMI1), a member of the Polycomb repressive complex 1 (PRC1) of transcriptional regulators, has been found to be highly expressed in tissue samples of primary and metastatic osteosarcoma from both dogs and humans." (PMID 40563676, 2025). "In addition, depletion of other CBX family members, such as CBX2 and CBX6, or PRC1 core subunits, Ring1a and Ring1b, did not consistently show to affect the mRNA level of Runx2 in these osteosarcoma cell lines." (PMID 32111827, 2020).
premature ovarian failure (2 papers, 2022 to 2024). "PRC1 dysfuction causes depletion of the ovarian reserve and leads to premature ovarian failure." (PMID 35948547, 2022). "Conditional knockout mice with dysfunctional PRC1 complexes in oocytes (PRcKO) exhibit total depletion of ovarian reserve and premature ovarian failure." (PMID 39545409, 2024).
renal cell carcinoma (2 papers, 2022 to 2025). "Despite its known effects in these cancers, PRC1's role in renal cell carcinoma (ccRCC) remains unexplored." (PMID 40093809, 2025). "In this study, we employed genomic-wide CRISPR screening and multi-omics techniques to elucidate the upregulation of the PRC1 gene in renal cell carcinoma (RCC), highlighting its pivotal role in the malignant progression of the disease." (PMID 40093809, 2025). "Our study showed that PRC1 was significantly overexpressed in renal cell carcinoma, and knockdown of PRC1 inhibited ccRCC cell proliferation, migration, both in vitro and in vivo, but the specific mechanism is not clear." (PMID 40093809, 2025).
retinal degeneration (2 papers, 2021 to 2024). Degeneration of the retina. "We have previously demonstrated that the polycomb-repressive complex-1 (PRC1) has a permissive role for the cell cycle activation during retinal degeneration, but we did not investigate the potential role of PRC2, which often interacts with PRC1." (PMID 34502238, 2021).
teratocarcinoma (2 papers, 2012 to 2021). A germ cell tumor characterized by the presence of an embryonal carcinoma component and a teratoma component. "REST can interact with PRC1 and PRC2 and maintains PRC1/2 binding to neuronal genes in the human teratocarcinoma NT2-D1 cells and mESCs." (PMID 34452335, 2021). "Here we present evidence for an interaction between the transcription factor REST, PRC1, and PRC2 and show that RNF2 and REST co-regulate a number of neuronal genes in human teratocarcinoma cells (NT2-D1)." (PMID 22396653, 2012).
triple-negative breast carcinoma (2 papers, 2022 to 2025). An invasive breast carcinoma which is negative for expression of estrogen receptor (ER), progesterone receptor (PR), and human epidermal growth factor receptor 2 (HER2). "PCGF5 is also a component of the PRC1 (non-canonical PRC1) complex: overall, PRC1 components can interact with oestrogen receptor alpha (ERα), and the factor FOXA1 in ER-positive breast cancer cells, as well as with BRD4 in triple-negative breast cancer cells." (PMID 40867231, 2025).
urothelial bladder cancer (2 papers, 2018 to 2020). "Even though epigenetic regulation of PRC1 expression in human cancers has not been reported, overexpression of PRC1 has been described in many cancers, such as urothelial carcinoma of the urinary bladder and adenocarcinoma of the colon." (PMID 32685988, 2020).
viral infection (2 papers, 2020 to 2021). "We have previously shown that the recruitment of PRC2, the deposition of H3K27me3, and the H3K27me3-promoted enrichment of PRC1 on the KSHV genome by 72 hpi depend on LANA during de novo viral infection." (PMID 31923286, 2020). "Several differentially expressed genes between the two trajectories (CTSG, PRC1, DEFA4, KIF15, TCEAL9, HMMR, CEP55, and AZU1) were overexpressed in patients with severe viral infection, but not in those with non-severe viral infection compared to HCs." (PMID 33765435, 2021).
adrenocortical carcinoma (1 paper, 2024). "For example, aberrantly high expression of PRC1, the most positively correlated gene, is associated with a poor prognosis in patients with adrenocortical carcinoma." (PMID 38173030, 2024).
AUTS2 syndrome (1 paper, 2022). "The largest body of evidence relating to the genetics, underlying molecular basis and phenotype of any PRC1-associated NDD is that of AUTS2 syndrome." (PMID 36547251, 2022).
biliary tract cancer (1 paper, 2016). "BMI1 is a core component of the polycomb repressive complex 1 (PRC1) and is up-regulated in biliary tract cancer (BTC), contributing to aggressive clinical features." (PMID 26623561, 2016).
brain tumor (1 paper, 2017). "While the contribution of this mutation to the pathogenesis of the tumor is not known at this time, a role of AUTS2 in deregulation of PRC1 can be a part in tumorigenesis of a brain tumor." (PMID 29445462, 2017).
breast invasive carcinoma (1 paper, 2020). "By comparison with the top 200 up-regulated genes in breast invasive carcinoma (BRCA) from GEPIA database, only three genes (KIF23, PRC1, CDCA3) were screened for further research." (PMID 32944002, 2020).
breast tumor (1 paper, 2016). "Also, the expression level of the PRC1 gene is significantly higher in breast tumor tissue, compared with adjacent normal tissue." (PMID 27705907, 2016).
Burkitt lymphoma (1 paper, 2026). A rare form of malignant mature B-cell non-Hodgkin lymphoma. "We show that CHD4 and PRC1 components are novel repressors of BZLF1 gene expression and that both are required to prevent spontaneous lytic reactivation in Burkitt lymphoma cells." (PMID 41841741, 2026).
cholangiocarcinoma (1 paper, 2022). A carcinoma that arises from the intrahepatic biliary tree (intrahepatic cholangiocarcinoma) or from the junction, or adjacent to the junction, of the right and left hepatic ducts (hilar cholangiocarcinoma). "In ovarian and cholangiocarcinoma, patient with abnormal expression of PRC1 had poor prognosis." (PMID 35816352, 2022).
chronic sinusitis (1 paper, 2025). "Besides, hsa-miR-6507-5p was significantly downregulated in chronic sinusitis with nasal polyps, and might serve as a protective factor in the development nasal polyps via targeting NCAPG2 and PRC1." (PMID 41200507, 2025).
clear cell renal cell carcinoma (1 paper, 2025). "Our genome-wide CRISPR screening identified PRC1 as a key gene in clear cell renal cell carcinoma." (PMID 40093809, 2025).
COVID-19 (1 paper, 2023). A disease caused by infection with severe acute respiratory syndrome coronavirus 2. "In our study, seven genes (BUB1, PRC1, KIFC1, RRM2, CDKN3, CCNB2, and MCM6) were involved in the interaction between COVID-19 and silicosis." (PMID 37278873, 2023). "Finally, submodule analysis showed that PRC1, KIFC1, BUB1, MCM6, CCNB2, CDKN3, and RRM2, which were hub-shared genes of silicosis and COVID-19, possessed the highest mCODE scores." (PMID 37278873, 2023).
cyst (1 paper, 2023). A sac-like closed membranous structure that may be empty or contain fluid or amorphous material. "Strikingly, we found that H2Aub, a repressive histone mark catalyzed by PRC1, decreased in wild-type testes specifically at the spermatocyte stage; H2Aub was bright in spermatogonia and somatic cyst cells throughout the testis, but H2Aub signal declined dramatically in spermatocytes." (PMID 37401420, 2023).